OR10D4P (olfactory receptor family 10 subfamily D member 4 pseudogene)
Description:
Odorant receptor.
Synonyms: formerly OR10D4; OR10D6P
Gene: Unprocessed pseudogene on chromosome 11 (124,093,592 to 124,094,532, reverse strand). Ensembl gene ENSG00000186268.
Subcellular location: Cell membrane